MMP2 (matrix metallopeptidase 2)
Diseases named in the same sentence as MMP2 in open-access papers (continued):
Sharing a sentence is not in itself a finding about the gene and the disease.
cancer (continued). "For these in vitro experiments, HT-1080 cancer cell spheroids were electroporated with a control siRNA, MMP-1 and MMP-2 siRNAs, or MT1 siRNA." (PMID 30903592, 2019). "The overexpression of many MMP family members, such as MMP2, MMP9 and MMP11 has been found to be involved in cancer progression 27-29." (PMID 31595150, 2019). "We also observed the up-regulation of TIM2 expression and down-regulation of MMP2 and MMP9 levels in EEL groups, which further proved the inhibiting ability of EEL on cancer metastasis." (PMID 31572063, 2019). "The overexpression of miR-149 increased the drug sensitivity of cancer cells and inhibited the EMT through the FOXM1/cyclin D1/MMP2 axis." (PMID 31552107, 2019). "The results of several studies have shown that PDPN is involved in ECM remodeling, and that the process of ECM degradation predominantly involves MMP-2 and MMP-9 whose expression correlates with prognosis in some cancer types." (PMID 30654768, 2019). "Many factors derived by activated fibroblasts, such as MMP2 and fibroblast growth factor 1 (FGF1), can promote profound proliferation of cancer cells." (PMID 31167491, 2019). "MMP-2 and MMP-9 play an important role in pathophysiological processes such as cell migration, angiogenesis, and the invasion and metastasis of malignant tumors." (PMID 31777578, 2019). "Some studies showed that overexpression of SOX2 promotes human cancer cell proliferation mainly through promoting migration and invasion via PI3K/AKT by increasing MMP2 expression." (PMID 31934531, 2019). "MC3353 displayed dose- and time-dependent antiproliferative activity in several cancer cell types, inducing cell death and affecting EMT through E-cadherin and MMP2 modulation." (PMID 31060628, 2019). "Based on the results, MMP2, MMP9 and MMP14 expression levels were also reduced in cells treated with ampelopsin E. Production of MMPs correlates with the ability of cancer cells to perform EMT." (PMID 31323836, 2019). "Although MMP1 and MMP2 are well-known regulators of cardiac ECM components, MMP11 has been observed in endometrium and human carcinomas." (PMID 31513610, 2019). "MMP-2 and MMP-9 (also called gelatinase A and B, respectively) have been correlated with the invasive stage of carcinomas due to their ability to degrade gelatin and collagen type IV, the main components in the basal membrane." (PMID 31554180, 2019). "The activity of specific MMP types such as MMP-2, MMP-9 and membrane type 1 (MT1)-MMP is upregulated in most human cancers." (PMID 30208169, 2018). "In our study, the down-regulations of MMP-2, MMP-9, and Vimentin reflected the inhibitory effects of APS on migration and invasion of MG63 cells, suggesting that APS exerted anti-cancer role in OS also by inhibiting cell migration and invasion." (PMID 30462772, 2018). "Activated CAFs further promoted cancer progression by secreting angiogenic cytokines, including VEGF, MMP2, MMP9, bFGF and TGF-β." (PMID 30591064, 2018). "The mRNA expression and protein levels of MMP-2 and MMP-9, critical factors in cancer cell migration, as well as the activity of MMP-9 also decreased or increased with ARP." (PMID 29464048, 2018). "MMP2 belongs to the matrix metalloproteinase (MMP) gene family, which are major extracellular enzymes involved in cancer initiation, progression, and metastasis." (PMID 30568862, 2018). "Invasion during metastasis requires the upregulation of proteolytic enzymes, such as MMP-2/9 or uPA, to degrade the ECM, thereby facilitating cancer cell invasion into the surrounding tissues." (PMID 30442941, 2018). "The expression level of MMP-2 and MMP-9 increases during the progression of many cancers, such as breast, endometrial and ovarian cancers, which closely correlates with cancer migration and poor prognosis." (PMID 29614094, 2018).
cancer (continued). "Malignant ascites-released membrane vesicles contain diverse activated proteases including MMP2, MMP9, uPA and ADAM17/TACE, together promoting ECM degradation and enhancing cancer cell invasiveness and metastasis." (PMID 28929459, 2018). "Both MMP-2 and MMP-9 were reported to degrade the basement membrane (BM), playing a key role in cancer cell invasion and metastasis." (PMID 29419740, 2018). "The overexpression of RBP4 stimulated the expression of matrix metalloproteinase MMP-2 and MMP-9, which degraded extracellular matrix and enabled cancer cells migration." (PMID 29642915, 2018). "Matrix metalloproteinase-2 (MMP2) and matrix metalloproteinase-9 (MMP9) are gelatinases of the matrix metalloproteinase family, which play a crucial role in cancer cell growth and migration due to their ability to degrade extracellular matrix proteins." (PMID 29882874, 2018). "Although STAT3 directly activates the transcription of MMP2 and MMP9 in cancer cells, the regulatory mechanisms in alveolar macrophages should be further validated." (PMID 30410547, 2018). "Recent findings indicated that several proteases, including MMP-2, MMP-3, MMP-9, presenilin 1, and CD26, are promoters and mediators of EMT processes in different cancer types." (PMID 30134935, 2018). "Some MMPs, including MMP-2 and MMP-9, are produced as inactive pro-enzymes from cancer cells and are then activated by proteolytic cleavage." (PMID 30336548, 2018). "Transient knock-down of Smoothened (Smo), a critical component of the hedgehog signaling pathway, inhibited the expression of MMP2 and MMP9 in CD44-positive cancer cells." (PMID 29747682, 2018). "The expressions of VEGF-α, MMP2, MMP9, bFGF and TGF-β were all increased from CAFs of human HCC cancer cell lines compared with the normal HSCs." (PMID 30591064, 2018). "It has been demonstrated that MMP-2/9 can regulate the degradation of the extracellular matrix (ECM), which plays an important role in cancer metastasis." (PMID 30231922, 2018). "Generally, destruction of the ECM requires the activation of proteolytic enzymes such as MMP-2 and MMP-922, and activation of MMP-2 and MMP-9 promotes cancer invasion and metastasis." (PMID 29712908, 2018). "MMP-2 and MMP-9 are known to be proteolytically activated by MT1-MMP and assist cancer cell invasion." (PMID 29507310, 2018). "Our recent study demonstrated that cancer cell migration and invasion is partly dependent on EMT process and matrix MMPs such as MMP2 and MMP9." (PMID 29300772, 2018). "In melanoma cells, microtubule-dependent traffic of MMP-2 and MMP-9 containing vesicles and their exocytosis promote cancer cell invasion." (PMID 30322133, 2018). "IR increases the migration and invasion capabilities of human cancer cell lines derived from CRC, lung cancer and glioblastoma, together with the upregulation of MMPs such as MMP-2 and MMP-9." (PMID 30336548, 2018). "In this contest, MMP-2 and MMP-9, play a critical role in cancer cell migration and invasion by stimulating the degradation of ECM and their increased expression is associated with disease progression." (PMID 29721201, 2018). "Cancer fibroblast and stromal cells had increased expression of MMP and MMP-related genes: MMP2, MMP11 and TIMP1." (PMID 30383866, 2018). "Several zinc‐containing matrix‐degrading endopeptidases (MMP‐1, MMP‐2, MMP‐3), which are known regulators of tissue remodeling in aging and cancer, were also included in the selected list of metformin targets." (PMID 29740925, 2018). "Prior studies indicate that highly expressed MMP-2 can facilitate the activation of gelatinase MMP-9, contributing to the invasion and metastasis of cancer cells." (PMID 30484490, 2018). "MMP2 and MMP9 are two important matrix proteinases in the MMP family that degrade type IV collagen, a major component of the basement membrane in cancers." (PMID 29849932, 2018).
cancer (continued). "Studies have shown that inhibition or reduction of VEGF, MMP2, MMP9, and CD31 activity leads to reduction of angiogenesis, invasion, and cancer cell metastasis." (PMID 30127820, 2018). "MMP2 and MMP9 use mainly collagen IV as substrate and digest the basement membrane to promote cell invasion in cancer cells." (PMID 29734379, 2018). "Matrix metalloproteinase 2 (MMP2) is a member of the Ca2+- and Zn2+-dependent endogenous protease family (MMPs), whose expression in tumors is reported to be correlated with carcinoma invasion and metastasis." (PMID 29850505, 2018). "Many studies have found that MMPs, in particularly MMP2 and MMP9, are important molecules in cancer tissue remodeling." (PMID 28587210, 2017). "In particular, MMP-2 and MMP-9 are known to degrade type IV collagen, which is the major component of the basement membrane, and induce cancer progression and metastasis." (PMID 28481901, 2017). "Expression of both Matrix Metalloproteinase 2 (MMP2) and Matrix Metalloproteinase 9 (MMP9) was higher in cancer microtissues than in fibroblast-free microtissues." (PMID 29112150, 2017). "It is well known that MMP‐2 and MMP‐9 are overexpressed and promote cancer cell invasion and metastasis in many cancers." (PMID 28846829, 2017). "In fact, our results demonstrated that, except MMP-7, antcin-H also inhibited other MMP gene expressions, such as MMP-2, MMP-3, and MMP-13, which play critical roles in cancer cell invasion." (PMID 29234409, 2017). "In our study, we found that three MMP family members (MMP2, MMP7 and MMP14) which had been verified to induce EMT progression in different types of cancer were decreased in two KIAA1199 knockdown GC cells." (PMID 28422983, 2017). "We also found that miR-200b-3p and miR-429-5p dually inhibited expression of PCNA, MMP2, and MMP9, protein biomarkers of cancer-cell proliferation and motility, in MDA-MB-231 and HCC1937 cells." (PMID 29156719, 2017). "Specifically, MMP-2 and MMP-9 inhibitor, termed 5a, has been proven to enhance apoptosis in cancer cells." (PMID 28746469, 2017). "Taken together, we provide a comprehensive in vitro analysis of MMP-2 and MMP-9 activity in Rb in several checkpoints that are deregulated in cancer." (PMID 28633655, 2017). "Type IV collagenase matrix metalloproteinases (MMPs), in particular, MMP-2 and MMP-9 and gelatinase A and gelatinase B, respectively, have been found to promote invasion and metastasis of malignant tumors." (PMID 29181405, 2017). "Mounting evidence has indicated that the inhibition of MMP-2 and MMP-9 activity reduces cancer cell metastasis in head and neck cancer." (PMID 29163852, 2017). "Activated Akt/NF-κB signaling pathway increased the expression of downstream proteins, such as MMP2 and MMP9, and finally result in cancer cell migration, invasion and metastasis." (PMID 29088737, 2017). "In the present study, up-regulations of MMP-2 and CA199 are the markers for increased proliferation of cancer cells." (PMID 28915621, 2017). "Two proteolytic enzymes—matrix metalloproteinases (MMPs) MMP-2 and MMP-9—have been found to have extensively elevated levels in malignant tumors." (PMID 28767067, 2017). "MMP2 and MMP9 are enzymes important for metastatic cancer cell to invade the basement membrane, and therefore are indicators of metastasis." (PMID 29156719, 2017). "MMP-2 and MMP-9 have been reported to play a critical role in cancer cell migration and invasion by contributing to the degradation of the ECM and cancer progression." (PMID 29267213, 2017). "Among the MMPs, MMP-2 and MMP-9 are the gelatinases expressed in cancer cells, and their proteolytic activity contributes to metastasis." (PMID 28481901, 2017). "In particular, we evaluated the effects of treatment with Ganoderma lucidum on the release of IL-6, IL-8, MMP-2 and MMP-9 and other inflammatory cytokines promoting cancer." (PMID 28264501, 2017).
cancer (continued). "To further study how PAM inhibits the metastasis of ES2 cells, we checked the expressions of matrix metalloproteinases (MMPs), especially MMP-2 and MMP-9, which are widely reported to directly promote the invasion ability of malignant cancers." (PMID 28729634, 2017). "Among all the involved proteases, MMP2 and MMP9 are the most essential for degradation of the basement membrane and so they play a major role in cancer invasion and migratio." (PMID 28881668, 2017). "ZR30’s inhibition of MMP2 activation was shown not only for GBM cells, but also for other types of cancer cells having overexpression of MMP2." (PMID 29290950, 2017). "Our study demonstrates, for the first time, how Ganoderma lucidum extracts can significantly inhibit the release of IL-8, IL-6, MMP-2 and MMP-9 in cancer cells under pro-inflammatory condition." (PMID 28264501, 2017). "COL11A1, COL6A1, MMP2, NID1, and FLT4 have been shown to have a positive role in regulating motility and invasion of various cancer cells." (PMID 28555007, 2017). "TNF-α can also induce the expression of many oncoproteins through NF-κB or p38 signaling, such as JAG1, Fascin, VEGF and MMP2/MMP9, to promote the development of cancers." (PMID 28938560, 2017). "Specifically, MMP-2 and MMP-9 are the most-studied MMPs in the context of cancer, including metastasis." (PMID 28507454, 2017). "MMP-2 and MMP-9 can degrade matrix collagen and basement membrane and correlate with the invasive and metastatic properties of cancer." (PMID 28678918, 2017). "Cancer stem cell (CD44 and N-cadherin) and migration (MMP-2 and -9) markers showed significant decrease in the levels in treated group compared to control." (PMID 28609459, 2017). "Matrix metalloproteinase MMP2 and MMP9 are well known for their role in cell migration and invasion of cancer cells." (PMID 28212565, 2017). "Inhibition of MMP-2 and MMP-9 expression and activity in cancer cells has been shown to prevent their migration and invasion." (PMID 28481901, 2017). "Matrix metalloproteinases (MMPs), including MMP2, MMP9 and MTI-MMP (MMP14), are critical mediators within invadopodia that promote cancer cell invasion." (PMID 28436416, 2017). "We next measured the effect of PA on mRNA and protein expression of MMP-2, MMP-9, TIMP-1, and TIMP-2 (which have critical roles in cancer cell migration and invasion) in HeLa cells by use of western blotting and RT-qPCR." (PMID 29267213, 2017). "The next step, performed in our study, is to look for changes in the expression of E-cadherin, MMP-2, VEGF-C and CD44v6 in cancer cells exfoliated from the vaginal stump and literature show that these are closely related to cancer cell invasion and metastasis." (PMID 29308376, 2017). "For example, the STAT3 transcription factor induces the expression of matrix metalloproteinase 2 (MMP-2), MMP-9, and epithelial–mesenchymal transition-related genes in promoting cancer cell invasion and metastasis." (PMID 28856117, 2017). "Possibly, like in some other cancer cells, FN1 induced specific matrix metalloproteinases expression, such as MMP9/MMP2, to promote invasion and metastasis." (PMID 28147311, 2017). "Together, these results support the conclusion that daurinol mediated FAK inhibition is important in inhibiting cancer cell invasion and that MMP2, MMP9, and uPA expression is regulated by FAK in both MDA-MB-231 and A549 cancer cells." (PMID 28915654, 2017). "One of the major implications of MMPs in cancer progression is their role in ECM degradation, and MMP2 and MMP9 is capable of degrading type IV collagen." (PMID 29228607, 2017). "Given the recent emphasis in the role of MMP-2 and MMP-9 in ECM degradation and cancer invasion we are focusing our studies on investigating MMP-2 and MMP-9 activity in Rb." (PMID 28633655, 2017). "A large number of literature studies shown that VEGF, MMP-2 and MMP-9 have been regarded as metastasis-related genes, which play important roles in cancer invasion and metastasis." (PMID 29156710, 2017).
cancer (continued). "We next examined the expression of MMP-2 and MMP-9, which are widely known as critical molecules involved in cancer invasion and metastasis." (PMID 28548944, 2017). "HMGB1 has been reported to mediate MMP2 and MMP9 expression in some inflammatory disorders and cancers." (PMID 28348451, 2017). "AGEs-RAGE signaling cascade induced the cancer cell invasion and migration partially through increasing expressions of RAGE, Sp1, and MMP2." (PMID 29262634, 2017). "Mere15, novel polypeptide, suppressed the expression of MMP-2 and MMP-9 and eventually inhibits cancer cell metastasis." (PMID 29233192, 2017). "Of the MMPs, a specific subset are the gelatinases (MMP-2 and MMP-9), which have been the subject of research for their high levels of expression in various malignant tumors and close relation with cancer cell metastasis." (PMID 28350337, 2017). "The cancer cells secrete MMP, and its dimer MMP2 is then activated by MT1-MMP; the MMP2 then degrades the ECM." (PMID 28638440, 2017). "Among MMPs, MMP-2, MMP-9 and membrane-type matrix metalloproteinases (MT-MMPs) are believed to play an important role in cancer invasion and metastasis." (PMID 29163852, 2017). "We also found that the hYSK1/CDKI complex increases the promoter activity of matrix metalloproteinase-2 (MMP-2), thereby enhancing the invasiveness and metastatic potential of cancer cells under hypoxic conditions." (PMID 29179500, 2017). "Cancer Clinical Trials with an anti-MMP-9 therapeutic antibody were recently initiated, prompting us to investigate the role of MMP-2, −9 in Rb metastasis." (PMID 28633655, 2017). "MMP-2, as a key protein in the ECM and basement membrane, that can promote carcinoma cell invasion and metastasis." (PMID 28915621, 2017). "Overexpression of MMP-2 and MMP-9 promotes cancer progression and is highly correlated with poor prognosis of cancer patients." (PMID 27733866, 2016). "The expression of MMP-2, MMP-9, and ADAM12m has been shown to have a crucial role in cancer cell invasion and metastasis through promoting degradation of numerous peri-cellular substrates." (PMID 27270327, 2016). "The objective of the present study was the identification of new NZIs selective toward MMP-2 and MMP-13, which are involved in cancer development." (PMID 27782083, 2016). "For example, MT3‐MMP can activate pro‐MMP‐2 9, while MMP‐2 is known to promote cancer cell invasiveness." (PMID 27292876, 2016). "Downregulation of S100A8 and S100A9 was further accompanied by decreased MMP2 and MMP9 expression in cancer cells, both in culture and in metastatic liver colonies." (PMID 27086923, 2016). "Class I HDACs, HDAC 1 and HDAC 2, have been shown to increase invasion through the upregulation of MMP-2 and MMP-9 in different cancer cell lines." (PMID 27506904, 2016). "Activation of MMPs, in particular MMP-2 and MMP-9, plays crucial roles in tissue matrix degradation, and thus, paves the way for cancer cell migration." (PMID 26760964, 2016). "BQ components further activated matrix metalloproteinase-2 (MMP-2) and MMP-9 in oral epithelial cells and cancer cells, contributing to the invasion and metastasis of OSCC." (PMID 26919242, 2016). "MMP2 and MMP-9 also contribute to BQ-related oral carcinogenesis by promotion of cancer invasion and metastasis." (PMID 26919242, 2016). "MMPs help cancer cells spread by breaking down the extracellular matrix (ECM) and other barriers MMP-2 and MMP-9 were previously reported to be involved in human tumorigenesis and cancer metastasis." (PMID 27042161, 2016). "Disruption of CD147 dimerization can prevent cancer metastasis effectively through attenuating MAPK activation and MMP-2 induction." (PMID 26882566, 2016). "In particular, MMP2, MMP9 and MMP14 have all been shown to promote cancer progression due to their ability to degrade basement membrane components." (PMID 27789576, 2016). "S100A8 and S100A9 knockdown significantly decreased MMP2 and MMP9 protein levels in the cancer cells." (PMID 27086923, 2016).